DEFB116 (defensin beta 116)
Description:
Has antibacterial activity.
Synonyms: DEFB-16
Tractability: Antibody: UniProt places it where antibodies can reach, with medium confidence; UniProt predicts a signal peptide or a membrane-spanning region; its Gene Ontology location is reachable by antibodies, with medium confidence.
Gene: Protein-coding gene on chromosome 20 (31,303,212 to 31,308,585, reverse strand). Ensembl gene ENSG00000215545.
Subcellular location: Secreted
Pathways (Reactome):
Immune System: Beta defensins; Defensins
Gene Ontology:
Biological process: innate immune response
Cellular component: extracellular region
Genetic constraint (gnomAD): Loss-of-function variants: 5 observed, 3.78 expected, observed/expected ratio (o/e) 1.32, 90% interval 0.64 to 1.91. That is too few expected variants to judge how well the gene tolerates losing a copy. Missense variants: 170 observed, 125.1 expected, observed/expected ratio (o/e) 1.36, 90% interval 1.2 to 1.54. Synonymous variants: 56 observed, 43.58 expected, observed/expected ratio (o/e) 1.28, 90% interval 1.04 to 1.61.
Homologues: Orthologues: chimpanzee DEFB116 (100% identical), macaque DEFB116 (96% identical), dog DEFB116 (71% identical), pig DEFB116 (67% identical), rat Defb29 (47% identical), mouse Defb29 (42% identical). Paralogues in human: DEFB121 (24% identical), DEFB108B (23% identical), DEFB115 (23% identical), DEFB127 (23% identical), DEFB104A (22% identical), DEFB104B (22% identical), DEFB123 (22% identical), DEFB129 (22% identical), DEFB108C (21% identical), DEFB118 (21% identical), DEFB119 (20% identical), DEFB132 (20% identical), and 7 more.